MPO (myeloperoxidase)
Diseases named in the same sentence as MPO in open-access papers (continued):
Sharing a sentence is not in itself a finding about the gene and the disease.
acute coronary syndrome (continued). "Myeloperoxidase has also been suggested as a potential inflammation biomarker in various diseases such as anemia, heart disease, and acute coronary syndrome." (PMID 37900082, 2023). "In a meta-analysis including 13 studies with 9090 subjects with acute coronary syndrome and a median follow-up of 11.4 months, Kolodziej and coworkers suggested that high MPO levels significantly predicted mortality with an OR of 2.0 (95% CI 1.4–2.9)." (PMID 37373746, 2023). "Myeloperoxidase (MPO) and global registry of acute coronary events (GRACE) risk scores were independently used to predict adverse outcomes in patients with acute coronary syndrome (ACS)." (PMID 35419382, 2022). "In patients with acute coronary syndrome, who received rosuvastatin on the first day, a significantly greater decrease in MPO activity was observed compared to that in the placebo group." (PMID 35624720, 2022). "Consistent with our results, evidence was recently reported for the acute in vivo release of neutrophil (CD66b+ and MPO+)-derived MVs after PCI in acute coronary syndrome patients, with blood sampling from the coronary circulation." (PMID 36140297, 2022). "A number of studies report that circulating MPO levels independently predict adverse cardiovascular events in patients with chest pain, acute coronary syndrome, or AMI." (PMID 34650427, 2021). "Many studies have linked myeloperoxidase (MPO), a neutrophil and inflammatory marker, to cardiac inflammation in the setting of acute coronary syndrome (ACS)." (PMID 31341419, 2019). "In this comprehensive systematic review and meta-analysis, we confirm the strong correlation between elevated plasma MPO levels and cardiac outcomes, including mortality, among patients with acute coronary syndrome." (PMID 31341419, 2019). "Since that time, MPO has been considered a circulating marker of related diseases such as acute coronary syndrome, CAD, and chronic heart failure." (PMID 29669993, 2018). "Myeloperoxidase (MPO) concentrations predict adverse clinical outcomes in setting acute coronary syndromes (ACS) and heart failure, but the prognostic role of MPO in SCAD with atherosclerotic burden is poorly understood." (PMID 29618370, 2018). "In this study, we have established a relationship between rIMT and biomarkers (creatinine, cystatin C and MPO) which have been suggested to be indicative of poor prognosis in populations with acute coronary syndrome." (PMID 28881821, 2017). "Next, we analyzed data from the Myeloperoxidase In the Diagnosis of Acute Coronary Syndromes (MIDAS) Study, a multicenter cohort which included 991 participants with suspected ACS from 18 US EDs and data for HEART Pathway risk assessment." (PMID 26800789, 2016). "We investigated the relationship between fasting plasma glucose (FPG) levels and the levels of the inflammatory factor, myeloperoxidase (MPO), in patients with acute coronary syndrome (ACS)." (PMID 26307104, 2015). "The levels of myeloperoxidase (MPO), a strong prooxidant enzyme, have a prognostic role in acute coronary syndromes." (PMID 23936799, 2013). "These multiple mechanisms help explain the strong predictive value of plasma MPO levels for acute coronary syndromes (ACS) in humans even after adjusting for traditional cardiovascular risk factors, Framingham risk score, or hsCRP." (PMID 20158910, 2010). "Serum MPO levels have prognostic value at 30-days and 6 months for emergency department (ED) patients with chest pain, as well as patients with acute coronary syndromes enrolled in the CAPTURE study." (PMID 23675127, 2009). "Therefore, MPO has been suggested as a potentially useful marker for the initial assessment of patients with acute coronary syndromes." (PMID 39810847, 2024). "Elevated MPO levels are present in CAD; also, its high levels may indicate a high risk of acute coronary syndrome (ACS)." (PMID 39292720, 2024). "MPO is widely recommended as an early biomarker for patients with acute coronary syndrome." (PMID 39810847, 2024).
acute coronary syndrome (continued). "Furthermore, patients with acute coronary syndrome showed elevated levels of serotonin, correlating with plasma levels of myeloperoxidase, which is released by neutrophils." (PMID 36675065, 2023). "Intriguingly, statins, which block 3-hydroxy-3-methylglutaryl CoA-reductase, were found to suppress MPO expression in macrophages at the gene and protein levels and reduce serum MPO levels in diabetic hemodialysis patients and patients with acute coronary syndrome." (PMID 36421487, 2022). "MPO, a leukocyte-derived enzyme, is an early marker of acute coronary syndrome." (PMID 35529262, 2022). "MPO is a powerful prognostic marker for clinical outcomes in patients with acute coronary syndrome." (PMID 31341419, 2019). "Thus, MPO inhibitors have been developed for the treatment of heart failure and acute coronary syndrome in humans." (PMID 30889221, 2019). "Notably, previous studies have clearly demonstrated a positive correlation between serum MPO and acute coronary syndrome in patients, strongly suggesting a role of MPO in instability of atherosclerotic plaque." (PMID 28069011, 2017). "Clinical studies also found that MPO serum levels could be used to predict the incidence of major adverse cardiac events (MACE) in patients with acute coronary syndrome (ACS)." (PMID 28069011, 2017). "MPO secretion leads to specific inflammatory pathways considered to be links with clinical manifestation of acute coronary syndromes (production of oxidant hypochlorous acid, degradation of the atheroma fibrous cap and its increased vulnerability to erosion or rupture)." (PMID 22014237, 2011). "Tests to assay serum MPO levels will soon become commercially available, but the test characteristics and timing of possible MPO elevation in acute coronary syndromes are unknown." (PMID 23675127, 2009). "On the other hand, the acute coronary syndrome was strongly linked to malondialdehyde low-density lipoprotein (MDA-LDL) as a sensitive biomarker of plaque destabilization and with myeloperoxidase (MPO) that, in high concentrations, also contribute to plaque destabilization." (PMID 34805304, 2021). "HDL-associated MPO was negatively correlated with PON1 activity in patients with type 2 diabetes and coexisting CVD, non-diabetic patients with chronic ischemic heart disease, and patients with acute coronary syndromes; the results similar to that observed by us in RA patients." (PMID 32967340, 2020). "In patients with acute coronary syndrome, pre-admission treatment with statins, beta blockers or ACE inhibitors reduced MPO levels." (PMID 26280875, 2016). "This study aimed to investigate the differences in level of several biomarkers, i.e. C-reactive protein, myeloperoxidase, soluble CD40 ligand and placental growth factor, between acute coronary syndrome and chronic stable angina patients." (PMID 26576922, 2015). "The concentration of these C-reactive protein, myeloperoxidase, soluble CD40 ligand and placental growth factor were significantly increased in acute coronary syndrome patients." (PMID 26576922, 2015). "Myeloperoxidase (MPO) is a predominantly leukocyte-derived enzyme, involved in the initiation, destabilization of atherosclerotic plaque and genesis of acute coronary syndromes." (PMID 24594096, 2014). "Finally, the timing of any possible MPO elevation during acute coronary syndromes is unknown." (PMID 23675127, 2009). "A parallel kinetic relationship between HAE and apoA-I concentration was observed when isolated HDL was enzymatically oxidized via myeloperoxidase (MPO), and in acute coronary syndrome (ACS) patients and patients with sickle cell disease in comparison to healthy subjects." (PMID 28767713, 2017). "Therefore, despite the fact that MPO cutoff value was not the same, stratifying patients based on a certain MPO cutoff provided valuable prognostic information in patients with acute coronary syndrome." (PMID 31341419, 2019).
Hypertension (67 papers, 2015 to 2026). The presence of chronic increased pressure in the systemic arterial system. "Time to event analysis showed that higher levels of MPO decreased the risk of all cancers combined (Hazard ratio for 1‐fold change of serum level: HR = 0.67, p = 0.033) and hypertension (HR = 0.72, p = 0.05)." (PMID 41316897, 2026). "Since smoking, alcohol consumption, and hypertension-related metabolic syndrome are risk factors for gastric cancer, these findings suggest that the relationship between MPO and PGR is more pronounced in high-risk populations for gastric cancer." (PMID 40547041, 2025). "As arterial hypertension is the most prevalent risk factor for vascular accidents in cats, this study was performed to investigate the MPO pattern in brains of cats with hypertensive encephalopathy (HE)." (PMID 39473196, 2024). "MPO has also been identified as a significant cause of pulmonary arteriole constriction and subsequent hypertension under hypoxic conditions in a murine model of pulmonary artery hypertension." (PMID 39061857, 2024). "Using Cox regression analysis, we found that higher levels of anti-MPO and creatinine, and hypertension, and AAV were independent factors associated with renal survival in patients with a-ANCA." (PMID 38234907, 2024). "Multivariable regression analyses revealed that serum MPO levels and activities remained independently associated with plaque progression, in addition to smoking, hypertension and CRP levels (all P < 0.05)." (PMID 36404308, 2022). "Hypertension is associated with oxidative damage and xanthine oxidase, myeloperoxidase, and glutathione peroxidase induced lipid peroxidation of crystalline lens proteins." (PMID 33213085, 2020). "Results of our current study indicated that hypertension was associated with increased systemic activity of pro-oxidant enzymes XO and MPO in patients with ARC." (PMID 29590254, 2018). "Additionally, the G allele was associated with higher plasma AOPP and myeloperoxidase (MPO) concentrations, lower eGFR, and arterial hypertension." (PMID 39857298, 2025). "Our results suggest that MPO polymorphisms could serve as potential markers for identifying women at higher risk of developing hypertensive disorders during pregnancy." (PMID 40806204, 2025). "In summary, this is the first study to provide evidence that MPO genotypes and haplotypes influence circulating MPO levels in hypertensive disorders of pregnancy and may contribute to disease susceptibility." (PMID 40806204, 2025). "In addition, a stronger association was found between MPO level and high blood pressure at high blood glucose concentration." (PMID 26451069, 2015). "Specifically, the inverse association between MPO and PGR was stronger in participants with hypertension (β = -0.018, 95% CI: -0.026 to -0.009) compared to those without hypertension (β = -0.008, 95% CI: -0.01 to -0.007)." (PMID 40547041, 2025). "Repeated injections of NET inducer PMA over 3 months into the tail vein of male BALB/c mice induced hypertension and was associated with higher expression of NET markers (MPO, citH3), suggesting that NET formation relates to increased BP." (PMID 39861371, 2025). "L-NAME-induced hypertension significantly enhanced the myocardial, renal, and aortic tissue levels of MPO (p < 0.05) compared to normal control rats." (PMID 39171117, 2024). "The serum MPO level correlated positively with hypertension (rs = 0.258, P < 0.001) and hyperlipidemia (CHO, TG, and LDL-C; all P < 0.01)." (PMID 37304868, 2023). "MPO-AAV, dialysis dependence, and hypertension were classified as independent associated factors for AS." (PMID 33481903, 2021). "The presence of MPO-AAV, dialysis dependence, and hypertension were independently associated factors for AS among the 6 categories." (PMID 33481903, 2021). "The multivariable logistic regression analysis showed that MPO-AAV, dialysis dependence, and hypertension were independently associated factors for AS." (PMID 33481903, 2021).
Hypertension (continued). "We found that the RAAS elements were overactivated under hypertension and were further elevated by HT or HF diet, while HT and HF diet enhanced MPO and TNF-α parameters as well as the expression of pERK1/2; SOD, GSH, and eNOS levels were decreased." (PMID 34733402, 2021). "History of hypertension, smoking history, 1 higher logarithmic NT-proBNP (Log10 NT-proBNP), 1 standard deviation (1SD) higher LVEF, and 1 higher Log10 MPO were significantly associated with LAVI ≥ 34 mL/m2." (PMID 33574408, 2021). "Accordingly, there was a significant positive correlation between the level of LLF and MPO activity, which probably reflects a prolonged pro-oxidant activity of MPO in patients with hypertension." (PMID 29590254, 2018). "Previous pilot studies, including ours, have reported suppressed interleukin-6, hs-CRP, MCP-1, myeloperoxidase (MPO), decreased oxidative injury of red blood cells and lymphocytes, improved redox status of serum albumin, and amelioration of hypertension." (PMID 28902900, 2017). "The TRF reversed systolic and diastolic hypertension, hypercholesterolemia, hepatic steatosis, impaired antioxidant defense, and myeloperoxidase hyperactivity triggered by the high-fat diet." (PMID 28880217, 2017). "Anti-MPO antibodies can be also be induced with hydralazine which was used for inpatient management of his hypertension." (PMID 26558120, 2015). "Furthermore, our result demonstrated that higher levels of anti-MPO, creatinine, and combined with hypertension and AAV were concomitant risks for renal injury in patients with a-ANCA." (PMID 38234907, 2024). "Our results indicated that MPO and inflammation may mediate pathophysiological process of hypertension to AF." (PMID 33460291, 2020). "This may suggest that, if relevant also to humans, other endotypes of hypertension may involve other ROS sources (mitochondria, xanthine oxidase, or myeloperoxidase)." (PMID 33170835, 2020). "MPO-derived oxidants present in the vasculature can further react with NO thereby reducing its availability, and probably contributing to vascular dysfunction and hypertension." (PMID 29590254, 2018). "I propose that several new parameters (NO, cfDNA, MPO, PCSK9, MyBPC3, microRNA, TAS, Pb, and Cd) with prognostic and/or predictive potential should be included in screening to confirm the need for the extensive testing of middle-aged men by healthcare professionals due to the risk of hypertension." (PMID 40136460, 2025). "Patients with essential hypertension (EH) and HHcy displayed higher plasma MPO-DNA (myeloperoxidase DNA) and cf-DNA (cell-free DNA) levels than patients with EH alone explained the effective NETs formation in hyperhomocysteinemia." (PMID 40413366, 2025). "Blockage of P2X7 receptors with BBG fully prevented excessive MPO activity in the gastric fundus of SHR animals, indirectly indicating that this compound tempered hypertension-induced gastric inflammation and leukocyte recruitment." (PMID 36856255, 2023). "MPO-ANCA (or P-ANCA) and PR3-ANCA (or C-ANCA) were positive in 50 (64.1%) and 17 patients (21.8%), respectively; 14 patients had T2DM and 17 had hypertension." (PMID 37275374, 2023). "When there is the development of hyperlipidemia, hypertension, smoking, etc., the LDL in the circulation continuously form Ox-LDL through lipoxygenase and myeloperoxidase." (PMID 35391927, 2022). "For example, a third of the study population suffered from arterial hypertension, which was recently shown to promote NET formation based on elevated levels of DNA–myeloperoxidase complexes and citrullinated histone H3." (PMID 36359376, 2022). "To date, studies have reported several risks of ESRD in AAV patients such as MPA, myeloperoxidase (MPO)-ANCA positivity, glomerular filtration rate < 50 mL/min, and hypertension." (PMID 33611672, 2021). "We selected 6 categorical variables of age, sex, hypertension, LDL-cholesterol, dialysis and MPO-AAV for multivariable logistic analysis." (PMID 33481903, 2021).
Hypertension (continued). "We previously produced an H2-dissolved hemodialysis solution and observed an improvement in hypertension, as well as decreases in plasma levels of MCP-1 and MPO in chronic hemodialysis patients." (PMID 29089029, 2017). "In the setting of adult male participants with hypertension, Charkiewicz and colleagues (2021) showed high levels of MPO in hypertension men compared to the control groups without the disease." (PMID 35740071, 2022). "A significant correlation between the LLF and MPO (U/L; n=69, r=0.255, P<0.05), between LLF and XO (U/L; n=69, r=0.244, P<0.05), and between MDA (μmol/L) and GPx (U/L; n=69, r=0.250, P<0.05) was also found in serum of patients with hypertension." (PMID 29590254, 2018). "However, we did not observe any association between FIB-5 and MPO-ANCA, ANCA positivity, and hypertension at diagnosis." (PMID 33611672, 2021). "We identified that the negative correlation between MPO and PGR was stronger in populations who smoked, drank alcohol, or had hypertension." (PMID 40547041, 2025). "The negative results of anti-MPO and anti-PR3 antibodies in all the groups of studied men exclude the development of NET-related autoimmune processes in the course of hypertension." (PMID 40136460, 2025).